TRPC6 (transient receptor potential cation channel subfamily C member 6)
Diseases named in the same sentence as TRPC6 in open-access papers (continued):
Sharing a sentence is not in itself a finding about the gene and the disease.
tumor (44 papers, 2008 to 2025). "One of the most dramatic alterations of gene transcription involved the TRPC6 gene (located at 11q21-q22.2) which has been recently implicated in tumour invasiveness." (PMID 23497198, 2013). "Moreover, high TRPC6 expression has been suggested to be associated with a higher Tumor Node Metastasis (TNM) classification of tumors." (PMID 32182937, 2020). "TRP channels, including TRPC6 and TRPM7, have been implicated in a variety of cellular processes that promote tumor growth, survival, and metastasis." (PMID 39768254, 2024). "Further, targeted inhibition of TRPC6 in combination with adriamycin in vivo demonstrates a synergistic anti-tumor effect." (PMID 37569884, 2023). "This suggests that TRPC6 targeting can potentially serve as a novel anti-tumor approach by alleviating MDR and suppressing HCC proliferation." (PMID 37569884, 2023). "Accordingly, shRNA-mediated TRPC6 inhibition increases tumour responsiveness to doxorubicin treatment, as shown by a five-fold tumour size reduction in the in vivo HCC xenograft compared to doxorubicin-only treatment." (PMID 35269437, 2022). "To date, studies have reported that the expression of TRPC6 channel in tumors is related to tumor-related factors, such as endothelial growth factor (EGF), vascular EGF, and platelet-derived growth factor." (PMID 35392906, 2022). "In summary, TRPC6 is a critical factor in tumorigenesis and tumor progression of different RCC entities." (PMID 36613622, 2022). "In the hypoxic tumor microenvironment, the TRPC6 channel participates in the continuous activation of PSCs, which is a typical feature of the PDAC microenvironment." (PMID 36187789, 2022). "In recent years, studies have found that the over-expression of TRPC6 promotes tumor proliferation, growth, and invasion." (PMID 35392906, 2022). "The tumor nuclear grading according to Fuhrmann was positively correlated with the amount of detected TRPC6, suggesting a significant function of TRPC6 in tumorigenesis and tumor progression." (PMID 36613622, 2022). "Similar to Orai1, TRPC6 is also overexpressed in ESCC tumor tissues compared with normal esophageal tissues in terms of both mRNA and protein levels and its high expression is associated with poor prognosis." (PMID 34012400, 2021). "Using a newly developed potent TRPC6 antagonist, a separate study also showed that inhibition of this Ca2+ channel suppresses proliferation of several GC cell lines as well as GC tumor growth in a xenograft model." (PMID 34012400, 2021). "Evaluating this finding have raised the possibility that inhibition of TRPC6 can increase the radiosensitivity of tumor cells and also inhibits angiogenesis in the therapy of ESCC." (PMID 32765303, 2020). "Another Ca2 + -permeable channel, transient receptor potential canonical 6 (TRPC6), exhibited a vital role in tumor growth, differentiation, and apoptosis with promising pharmaceutic target values." (PMID 30134903, 2018). "Recent studies suggest that TRPC6 and intracellular Ca2+ play an important role in tumor metastasis." (PMID 28030826, 2017). "Recent reports indicated that TRPC6 also regulates the sustained elevation of basal calcium to influence tumour malignant behaviours." (PMID 27011063, 2016). "Based on this evidence, we concluded that by modulating sustained intracellular calcium aggregation, the overexpression of TRPC6 has crucially important effect on the adaptive behaviours of tumours." (PMID 27011063, 2016). "Second, TRPC6 expression is enhanced in a variety of primary neoplasms as compared to normal paratumour tissues, including RCC." (PMID 25126575, 2014).
tumor (continued). "Increased TRPC6 mRNA and gene dosage was detected in both, cell lines and tumor tissues, revealing that this molecular alteration can be pathologically relevant in HNSCC." (PMID 23497198, 2013). "Using semi-quantitative PCR, we analyzed TRPC6 mRNA expression in tumour and normal tissues from 3 individual patients." (PMID 18452628, 2008). "Regarding TRPC6 channel protein expression with tumour grade, we found that TRPC6 was expressed in 73.3% and 68.4% of grade I and grade II respectively, and increased to 80% in grade III." (PMID 18452628, 2008). "By downregulating TRPC6, dexamethasone could potentially impair tumour growth by disrupting calcium-dependent signalling." (PMID 40046334, 2025). "TRPC6 is another TRPC member to be regulated by tumour microenvironmental clues, such as hypoxia." (PMID 35806388, 2022). "Specifically, transient receptor potential channels (including TRPC6) which are key regulators of intracellular calcium homeostasis are also involved in the main processes of metastasis such as migration, invasion, and tumor vascularization." (PMID 34575190, 2021). "Moreover, treatment of xenografted GC nude mice with a TRPC6 blocker resulted in the inhibition of the development of tumor." (PMID 34012400, 2021). "Indeed, TRPC6 was found to affect different hallmarks of GBM including tumor growth, cell survival, invasiveness and angiogenesis." (PMID 33928077, 2021). "The expression levels of T-cell markers, such as CD28 and CD3 epsilon, were not affected by the risk haplotypes, so the expression reduction in TRPC6 and other genes involved in T-cell activation was not due to the absence of T-cells within the tumor." (PMID 25642983, 2015). "Importantly, amplification and concomitant overexpression of TRPC6 was also found in HNSCC tumour samples." (PMID 23497198, 2013). "Comparison of TRPC6 expression to tumour characteristics on 49 patients using χ2 analysis." (PMID 18452628, 2008). "In tissue stem cells, the high communication activity of CD99 may be associated with cell migration and invasiveness in the tumour microenvironment, promoting tumour cell spread and metastasis, suggesting that XBP1, TRPC6 and TTC28 may promote tumour development." (PMID 40046334, 2025). "In addition, the inhibition of TRPC6 decreased tumor formation in a mouse xenograft model." (PMID 32182937, 2020). "Consequently, inhibition of TRPC6 by acidic pHe may impair neutrophils’ migration and prevent them from leaving the acidic tumour microenvironment, thus contributing to its progression and metastasis by releasing ROS, secreting pro-tumour factors and inducing drug resistance." (PMID 35806388, 2022). "High expression of TRPM4 and TRPM7 was detected in primary tumor biopsies, while TRPV4, TRPC4, TRPC6 and especially TRPV6 expression was limited, while the expression of TRPC1 and TRPV2 are moderately expressed." (PMID 34936030, 2021). "In human HCC tissues, the expression of both TRPC6 and the (Na+-Ca2+) exchanger was higher in human HCC tissue compared to that in non-tumor tissue." (PMID 32987945, 2020). "In contrast, both tumour, MCF-7 and hBCE lysates produced a 97 kDa band corresponding to the expected size of full length TRPC6." (PMID 18452628, 2008). "We next compared the expression of TRPC6 with LNM, estrogen receptor (ER) expression, and tumour grade." (PMID 18452628, 2008). "A study investigating mRNA expression levels of the TRP channels in human CRC tissue versus normal colon mucosa detected an increase in gene expression of TRPM8, TRPV6, and TRPV1 and a lower expression of TRPV4, TRPM4, TRPV3, TRPC6, and TRPV5 in the tumor tissues of CRC compared to normal tissues." (PMID 32182937, 2020). "For example, TRPC6 channels targeting could affect VEGF release from tumor cells as well as EC migration and tumor vascularization." (PMID 24204345, 2013).
tumor (continued). "The high interaction of tissue stem cells with collagen may affect the tumour microenvironment by promoting extracellular matrix synthesis and degradation, and influencing tumour growth and angiogenesis, suggesting that XBP1, TRPC6 and TTC28 may influence tumour growth and angiogenesis." (PMID 40046334, 2025). "The role of FN1 in tissue stem cells with high communication intensity may facilitate interactions with other cells in the tumour microenvironment by supporting tumour cell attachment and spread, suggesting that XBP1, TRPC6 and TTC28 may influence the tumour microenvironment." (PMID 40046334, 2025). "However, whether these effects on tumor migration are dependent on the impact of TRPC5 and TRPC6 activity on cell contractility and motility remains to be clarified." (PMID 33132914, 2020). "Immunohistochemistry for TRPC6 confirmed the qPCR data, as expression of the channel was observed in ECs in normal areas (n = 6/10) (Figure 2adi), while a negative staining was obtained in ECs in all tumor areas (n = 10/10) (Figure 2adii)." (PMID 31288452, 2019). "Furthermore, we found that the overexpression of TRPC6 protein levels were not correlated with tumour grades, estrogen receptor expression or lymph node positive tumours." (PMID 18452628, 2008). "In addition, in HCC tissues, we found that TRPC6 expression is much higher in tumour tissues than in pericancerous tissues and is markedly related to a higher TNM classification (data not shown), suggesting that TRPC6 is closely associated with HCC’s malignant behaviours." (PMID 27011063, 2016). "Due to the important role of TRPC6-mediated Ca2+ signaling, it is not surprising to see that the inhibition of TRPC6 leads to cell cycle arrest via Cdk1 in ESCC cells and decreased tumor formation in a mouse xenograft ESCC model." (PMID 34012400, 2021).
cardiovascular disease (6 papers, 2020 to 2025). "Specifically blocking lysoPC-induced iPLA2β activation in ECs should prevent TRPC6 activation and preserve EC migration, thereby improving endothelial healing after interventions for cardiovascular diseases." (PMID 34509476, 2021). "Our findings highlight the pivotal role of TRPC6-mediated Zn2+ influx in modulating VSMC phenotypic plasticity and vascular remodeling, providing novel insights into its potential as a therapeutic target for cardiovascular diseases." (PMID 40001570, 2025).
neurological disorders (5 papers, 2020 to 2025). "Transient receptor potential canonical 6 (TRPC6) channels are promising drug targets for kidney, lung, and neurological diseases, making a detailed understanding of their regulation crucial to developing novel channel modulators with more precise modes of action." (PMID 41373637, 2025).
infection (4 papers, 2016 to 2022). The state of being infected such as from the introduction of a foreign agent such as serum, vaccine, antigenic substance or organism. "The difference in F485,cell across our experimental groups strongly affected calculation of F. TRPC6-eGFP and eGFP infection at 10 and 20 MOI yielded similar levels of bleed-through as we found in uninfected NRVMs (data not shown)." (PMID 32116757, 2020). "Quantification of anti-TRPC6 antibody signal in these images is consistent with the visual impression that TRPC6-eGFP infection leads to a strong increase vs. eGFP infection." (PMID 32116757, 2020). "After 24 h infection, [Ca2+]i was significantly enhanced in TRPC6 overexpressed neurons compared to control group (GFP) in response to glutamate application." (PMID 28400714, 2017). "Enhancement of TRPC6 expression using AdCMV-TRPC6-GFP infection in WT neurons increased [Ca2+]i in response to glutamate application compared to AdCMV-GFP control." (PMID 28400714, 2017).
cardiac disease (3 papers, 2020 to 2023). "There was some indication that severe cardiac disease in the elderly might be associated with a decreased area of TRPC6-immunoreactive myocardium in the analyzed locations." (PMID 36661921, 2023). "In summary, in the elderly, TRPC6-protein is widely and homogenously distributed, and severe cardiac disease might be associated with less TRPC6-immunoreactive myocardial area." (PMID 36661921, 2023). "Thus, the present study mapped TRPC6-protein distribution in select anatomic locations associated with cardiac disease in the context of an orienting pathological assessment." (PMID 36661921, 2023). "Additionally, there were hints that these varying degrees of heart disease might be associated with differences in the TRPC6-immunoreactive myocardial area." (PMID 36661921, 2023). "Such a somehow “targeted” analysis would again provide further insights in the involvement of TRPC6 in cardiac disease." (PMID 36661921, 2023). "Two donors with more severe heart disease showed smaller areas of myocardial TRPC6-immunoreactivity overall compared to the other 3 donors." (PMID 36661921, 2023). "Further studies complementing the mapping of TRPC6-protein distribution on a subcellular level bear the potential to provide further understanding of TRPC6 in cardiac disease." (PMID 36661921, 2023). "TRPC6 was upregulated in response to activated calcineurin and pressure overload, further indicating a role in cardiac disease." (PMID 32116757, 2020). "The involvement of TRPC6 in cardiac diseases has made it a target for treatment." (PMID 32116757, 2020). "Thus, together with the involvement of the autonomic nervous system in cardiac diseases, we might speculate that TRPC6-protein expression is additionally linked with cardiac disease via the autonomous nervous system also and not by “direct” TRPC6-expression in the myocardium only." (PMID 36661921, 2023).
inflammation (3 papers, 2020 to 2023). Aberrant reaction of the microcirculation characterized by movement of fluid and leukocytes from the blood into extravascular tissues. "TRPC6 also plays an important role in immune-mediated kidney injuries by regulating tubulointerstitial inflammation and the further development of kidney inflammation." (PMID 38003608, 2023). "For example, podocyte- specific TRPC6 KO animal models should be developed to investigate the contribution of TRPC6 to antigen presentation in podocytes during renal inflammation." (PMID 38003608, 2023). "Utilizing TRPC6−/− mice and TRPC6-selective inhibitor, we found that TRPC6 contributed to O3 inhalation-induced airway inflammation." (PMID 32139669, 2020). "Moreover, we revealed a critical role of intracellular calcium homeostasis in the pathogenesis of such diseases and proposed that targeting TRPC6 might provide a novel therapeutic approach to prevent and treat oxidative stress-induced airway inflammation." (PMID 32139669, 2020).
kidney (2 papers, 2022 to 2023). "For example, TRPC6 is strongly associated with the infiltration of immune cells into the kidney and consequently with kidney inflammation in the context of ischemia/reperfusion kidney injury (I/R), unilateral ureteral obstruction (UUO) and DKD." (PMID 38003608, 2023). "In this review, we present an overview of the current knowledge of how TRPC6 coordinates the immune cell functions and propose the hypothesis that TRPC6 might play a pivotal role in the development of kidney injury via its role in the immune system." (PMID 38003608, 2023). "TRPC6 activation may also be enhanced by the combination of receptor binding and mechanical stimulation and has been reported to play an important role in mediating kidney injury in DM." (PMID 34866402, 2022).
immune disorder (1 paper, 2017). "As regards to the non-syndromic forms, some are related to a still not completely understood underlying immune disorder, while an increasing number is found to be caused by mutations in genes highly expressed in podocytes (e.g. NPHS1, NPHS2, CD2AP, PLCE1, ACTN4, TRPC6, and INF2)." (PMID 28298181, 2017).
TRPC6 also shares sentences with these, for which no sentence is quoted: type 2 diabetes (6 papers); hypertrophic cardiomyopathy (4); non-small cell lung carcinoma (3); glomerulopathy (2); lupus nephritis (2); myocardial ischemia (2); Parkinson disease (2); adenocarcinoma (1); aneurysm (1); autoimmune disease (1); autosomal dominant disease (1); bladder cancers (1); brain cancer (1); breast ductal adenocarcinoma (1); breast tumour (1); cardiac arrhythmias (1); cervical adenocarcinoma (1); cervical squamous cell carcinoma (1); ciliopathies (1); colon cancer (1); coronary heart disease (1); cystic kidney disease (1); degenerative disc disease (1); dependent (1); diabetic retinopathy (1); disc degeneration (1); end stage renal disease (1); essential hypertension (1); Fabry disease (1); Focal cortical dysplasia (1).
A further 31 diseases each share a sentence with TRPC6 in 1 paper.